PSAT1 (phosphoserine aminotransferase 1)
Diseases named in the same sentence as PSAT1 in open-access papers (continued):
Sharing a sentence is not in itself a finding about the gene and the disease.
breast carcinoma (continued). "Former studies have illustrated that serine biosynthesis has a key role in bone metastatic breast cancer, and three enzymes, PSAT1, phosphoserine phosphatase and phosphoglycerol dehydrogenase, are in charge of the phosphorylation pathway of L-serine biosynthesis." (PMID 36105075, 2022). "Given that breast cancer is a heterogenous disease, commonly classified into 5 to 10 intrinsic subtypes, the association of IKBKE and PSAT1 might be driven by subtype‐specific expression." (PMID 32783398, 2020). "Furthermore, gene expression data of a cohort of ER positive breast carcinomas was used to gain insight into the role of PSAT1 in tamoxifen resistance." (PMID 28522855, 2017). "Psat1 is a phosphoserine aminotransferase involved in serine biosynthesis whose expression has been shown to be up-regulated in colon adenocarcinoma, colorectal cancer and breast cancer." (PMID 20959002, 2010). "Additionally, PSAT1 methylation status was studied in various cancer types and found to have a negative relationship with dysfunctional T cell phenotypes and shorter survival times of the breast cancer." (PMID 36105075, 2022). "However, in breast cancer cells with amplified serine biosynthesis, Psat1 contributes a significant fraction of glutamine‐derived carbon flux to α‐KG, indicating that Psat1 can play an important role in Krebs cycle anaplerosis of glutamine‐derived carbon in cancer cells." (PMID 31036704, 2019). "We also show that breast cancer cell growth and NAT10 downstream genes PHGDH and PSAT1 are regulated by NAT10 in an RNA helicase activity–dependent manner." (PMID 40138393, 2025). "Among the four main breast cancer subtypes, the highly proliferative basal-like tumors typically exhibit high levels of GPT2 and PSAT1 expression, while GLUD1/2 expression is relatively low." (PMID 39973065, 2025). "Among all main metastasis sites of breast cancer, brain metastases exhibited the highest levels of NAT10, PHGDH, and PSAT1, followed by liver metastases." (PMID 40138393, 2025). "We further investigated the expression of NAT10, PHGDH, and PSAT1 in the AURORA US Metastasis Project (GSE193103), a larger cohort with paired breast cancer metastases and primary tumors." (PMID 40138393, 2025). "For the upstream regulation of PSAT1, we previously reported that PSAT1 can be transcriptionally activated by the transcription factor ATF4 in breast cancer." (PMID 39199378, 2024). "In breast cancer cells with bone metastases, the SSP pathway is promoted by upregulating PSAT1 to increase glutamine synthesis and decrease glucose dependence." (PMID 39199378, 2024). "And in primary breast cancer, the upregulation of PHGDH and PSAT1 is also significantly related to the shortening of overall survival time and the malignancy of breast cancer." (PMID 36998464, 2023). "In terms of mechanism, the decreased expression of kinase C zeta (PKC-ζ) in bone-derived breast cancer cells led to the upregulation of PHGDH, PSAT1 and PSPH, consequently promoted the utilization of glutamine through serine biosynthesis." (PMID 36998464, 2023). "Compared to breast cancer cells with low bone metastatic activity, the expression of serine metabolic enzymes (including PHGDH, PSAT1 and PSPH) was increased in breast cancer cells with high bone metastatic activity." (PMID 36998464, 2023). "Experimental studies have shown that CDKN2A, PSAT1, HMGB1, ELAVL1, and SLC7A11 were up-regulated in TNBC, ASNS and LAMP2 were up-regulated in breast cancer and CAV1 was down-regulated in breast cancer, and HELLS was up-regulated in other tumors." (PMID 36568247, 2022). "Its expression increases in breast cancer stages I to II, but in stages III to X, the expression of PSAT1 gradually decreases." (PMID 36105075, 2022). "Analogous results were obtained with the CDK12 inhibitor, THZ531 which, in line with the effects observed in CDK12-OE MCF10A cells, inhibited PSAT1 and MTHFD1 expression in CDK12HIGH breast cancer cells both at the mRNA and protein level." (PMID 35550508, 2022).
breast carcinoma (continued). "Hypoxia has been shown to induce expression of PHGDH, PSAT1 and PSPH in breast cancer cells and PHGDH has been shown to be overexpressed in various cancer types, including colorectal, non-small cell lung, cervical and breast cancers." (PMID 36226069, 2022). "PSAT1 knockdown sensitizes tamoxifen-resistant MCF7 breast cancer cells to tamoxifen, suggesting that PSAT1 contributes to tamoxifen resistance in MCF7 breast cancer cells." (PMID 36059650, 2022). "Compared with breast cancer cells with weak bone metastasis activity, the expression of de novo serine synthesis enzymes, including PHGDH, PSAT1, and PSPH, is increased in breast cancer cells with high bone metastasis activity." (PMID 33926551, 2021). "Regarding bone metastasis, breast cancer cells show increased serine biosynthesis through the expression of phosphoglycerate dehydrogenase (PHGDH), phosphoserine aminotransferase, (PSAT1), and phosphoserine phosphatase (PSPH)." (PMID 33915900, 2021). "PSAT1 can be directly activated by ATF4 and its expression is significantly increased in a variety of tumors, including breast cancer, ESCC, etc.." (PMID 32974142, 2020). "To evaluate influence on PARP1 activity, we down-regulated the expression of RIT1, PSAT1 and INCENP by using siRNA and analyzed the level of PARylation in MCF7 breast cancer cell line." (PMID 31105872, 2019). "A number of studies have suggested overexpression of PSAT1 protein as a poor prognostic marker in colorectal cancer, esophageal squamous cell carcinoma, NSCLC and ER(−) breast cancer." (PMID 31861486, 2019). "Promoter methylation of six genes (APC, CCND2, FOXA1, PSAT1, RASSF1A, and SCGB3A1) in ctDNA in breast cancer patients was confirmed as cancer-specific, although with a variable performance." (PMID 31752198, 2019). "PSAT1 mediates carbon metabolism and the TCA cycle, which provides energy and increases biomass in non-small cell lung cancer (NSCLC), breast cancer and colorectal cancer." (PMID 31861486, 2019). "Among 5 different cancer cell lines, MCF7 (CD44-low breast cancer) and MDA-MB-231 (CD44-high breast cancer) expressed either PHGDH or PSAT1, and PSPH." (PMID 29674746, 2018). "Cancer cells with LKB1 loss increase the expression of phosphoserine aminotransferase 1 (PSAT1), phosphoserine phosphatase (PSPH) and serine hydroxylmethyltransferase (SHMT1/2) involving de novo serine synthesis pathway (SSP) in breast cancer." (PMID 28931725, 2017). "Interestingly, PSAT1 expression was dramatically up-regulated in ER-negative breast cancers compared with ER-positive BC and normal tissues (P < 0.0001)." (PMID 29216929, 2017). "TAZ/YAP reprogram cellular energetics to promote the dependence of breast cancer cell growth on exogenous Gln, and TAZ/YAP induced GOT1 and phosphoserine aminotransferase (PSAT1) expression to promote the conversion of Gln to α-KG, and then to support cell growth." (PMID 39777342, 2024). "It has been shown that the activity of enzymes such as phosphoserine aminotransferase 1 (PSAT1), phosphoglycerate dehydrogenase (PHGDH), and phosphoserine phosphatase, which catalyze the synthesis of serine de novo, have increased expression in breast cancer." (PMID 39852119, 2024). "PSAT1, CA6 and CA9 are part of the Metabolic Pathways and affect the growth and migration of breast cancer cells MIR100 and MIR124-2 are two MicroRNAs within the same signaling pathway that induce apoptosis and cell cycle arrest in breast cancer cells through multiple genes." (PMID 38254021, 2024). "Additionally, combination treatment with YAP/TAZ or PSAT1 siRNA and tamoxifen significantly reduces mTORC1 activity and survivin expression in tamoxifen-resistant MCF7 breast cancer cells." (PMID 36059650, 2022). "In breast cancer, YAP/TAZ guide a metabolic reprogramming to promote a close dependence of tumor cells on exogenous glutamine by inducing the expression of glutamic-oxaloacetic transaminase (GOT1) and phosphoserine aminotransferase (PSAT1)." (PMID 33800464, 2021).
breast carcinoma (continued). "Moreover, SCUBE2, TMEM26, and SMOC2 were validated as subtype-specific coding genes in luminal A breast cancer, CDK12 and SDC1 in HER2 breast cancer and PSAT1 in triple negative breast cancer in TCGA and GEO datasets." (PMID 31801944, 2019). "Across a set of breast cancer cell lines, ER-negative breast cancer cell lines had higher PSAT1 protein expression compared with non-transformed MCF-10A and MCF-7 (ER-positive breast cancer cell lines)." (PMID 29216929, 2017). "Interestingly, PSAT1 and PSPH, the other two enzymes involved in serine biosynthesis, are also highly expressed in most ER− breast cancer cells." (PMID 24318446, 2013). "Given that previous studies have shown that GSK-3β is a promising target for cancer treatment, further research on the mechanism of PSAT1 and GSK-3β in ER-negative breast cancer may provide more valuable insight into optimal treatments for this type of breast cancer." (PMID 29216929, 2017). "In addition to DNA methylation, we analyzed PSAT1 chromatin immunoprecipitation sequencing (ChIP-seq) data for several histone H3 modifications in three luminal (MCF7, ZR751, and MDAMB361) and four basal (MDAMB231, MDMB436, MDAMB468, and HCC1937) breast cancer cell lines." (PMID 35045283, 2022). "However, these gene expression patterns clearly show that IKKε‐mediated expression of PSAT1 and the SBP enzymes, demonstrated in our in vitro experiments, is potentially also functional in a subset of clinical samples, suggesting the pathophysiological importance of the pathway in breast cancer." (PMID 32783398, 2020). "Inhibition of phosphoserine aminotransferase 1 (PSAT1), a downstream target of ATF4, was proposed in estrogen receptor–negative breast cancer." (PMID 39964754, 2025). "Surprisingly, chemical/genetic disruption of SBP did not delay BL and breast cancer xenografts growth, suggesting the existence of mechanisms compensating the PHGDH/PSAT1 absence in vivo." (PMID 32138178, 2020). "In addition, the possible ferroptosis mechanisms of CDKN2A, PSAT1, SLC7A11, LAMP2, CAV1, and HMGB1 in TNBC and ASNS, ZFP69B, ELAVL1, TF, HELLS, and DPP4 in breast cancer have not been reported." (PMID 36568247, 2022). "Importantly, in the explanted tumors with PSAT1 or PHGDH knockdown, there was no re-expression of the enzymes, indicating that disruption of SBP in the breast cancer cell model is not sufficient to delay the growth of an established tumor." (PMID 32138178, 2020).
lung carcinoma (22 papers, 2016 to 2026). "In addition, the expression of PSAT1 in lung cancer was significantly positively correlated with tumor mutational burden, and negatively correlated with tumor immune dysfunction and rejection." (PMID 37147729, 2023). "PSAT1 encodes a putative oncogene protein noted to be overexpressed and associated with unfavorable prognosis in a number of tumor types including breast and lung cancer." (PMID 31261735, 2019). "Molecular docking was employed to explore the binding affinity between the most active compounds (7a and 7g) and two key enzymes, PHGDH and PSAT1, which play vital roles in the progression of lung cancer." (PMID 40013064, 2025). "Phosphoserine aminotransferase 1 (PSAT1) accumulates nuclear PKM2 translocation to facilitate lung cancer cell migration, while the acetyl-mimetic mutant of PKM2 (K433Q) affected PSAT1-mediated cell migration." (PMID 38910890, 2024). "This is consistent with our research results that our findings also showed that the expression of PSAT1 in lung cancer tissues was higher than that in normal tissues." (PMID 36105075, 2022). "Taken together, our findings suggest that nuclear PKM2 translocation contributes, in part, to PSAT1-mediated cell migration under EGFR activation in lung cancer." (PMID 34439090, 2021). "To extend these findings and investigate the clinical relevance of PSAT1 in EGFR-mutant lung cancer, we analyzed microarray datasets from patients with EGFR-mutant lung tumors for a comparative expression analysis and correlation with clinical outcomes." (PMID 34439090, 2021). "Further, the depletion of PSAT1 suppresses lung cancer cell movement that can be partially restored by the compartment expression of PKM2." (PMID 34439090, 2021). "In lung cancer, PSAT1 can promote cell invasion by activating MMP1 pathway and was found as a novel predictor in stage I non-small cell lung cancer." (PMID 29297280, 2017). "Molecular docking was employed to explore the potential interactions between the most active compounds (7a and 7g) and two key enzymes, human 3-phosphoglycerate dehydrogenase (PHGDH) and phosphoserine aminotransferase (PSAT1), which play vital roles in the progression of lung cancer." (PMID 40013064, 2025). "It has been suggested that PSAT1 may be a new biomarker for the survival of lung cancer patients and for predicting the efficacy of immunotherapy." (PMID 37147729, 2023). "Therefore, we conclude that, in response to EGFR activation, PSAT1 contributes to lung cancer cell migration, in part, by promoting nuclear PKM2 translocation." (PMID 34439090, 2021). "Notably, tumor-initiating cells display an increased expression of PSAT1, further emphasizing the functional significance of PSAT1 in lung cancer progression." (PMID 34439090, 2021). "In addition, human KRAS‐mutant lung cancer cell lines harboring NF1 mutations (i.e., H2030 and H2347) showed marked sensitivity to glutaminase and PSAT1 inhibition, while those with WT NF1 (i.e., H23, H2009, and H1792) displayed less sensitivity." (PMID 31036704, 2019). "Three regions: 3p14.2 (deletion), 9p21.2q21.31 (amplification), and 20q13.12 (amplification) were commonly found in HN4 and HN31 as the same cluster in our analysis, and five genes (FHIT, MMP9, GNA14, GNAQ, and PSAT1) were involved in tumorigenesis in lung cancer and colon cancer." (PMID 27501229, 2016). "Therefore, our findings supported the suggestions that vitamin D may be a therapeutic agent in patients with pulmonary fibrosis and lung cancer, though not only through the regulation of PSAT1 but also the SHMT1 gene." (PMID 38203636, 2023). "In this study, we identify key enzymes in the serine synthesis pathway (SSP), namely PHGDH, PSAT1 and PSPH, as well as the serine transporter SLC1A4, which are significantly overexpressed in lung cancer and correlate with poor patient prognosis." (PMID 41702885, 2026).
lung carcinoma (continued). "Our analysis of Kaplan–Meier plots derived from data on 1925 lung cancer patients clearly confirmed the strong oncogenic role of HK2, LDHA, PHGDH, PSAT1, SHMT2, MTHFD2, c-Myc, and ATF4 (CREB-2) in lung cancer." (PMID 37233697, 2023). "Elevation of key SSP enzymes, such as PHGDH, PSAT1, and PSPH, is an important factor in the malignant progression of lung cancer cells and cancer drug resistance." (PMID 36699468, 2022). "We further found that both PSAT1 and PKM2 exhibited a nuclear translocation in response to EGFR activation in lung cancer cells whereas PSAT1 suppression abrogated the PKM2 nuclear localization." (PMID 34439090, 2021). "All data together indicated that the downregulation of c-Myc, HK2, PKM2, LDHA, PHGDH, PSAT1, cyclin D1, and CDK6 in lung cancer cells was related to the ubiquitin-protein degradation pathway, which was the result that the USP28 was inhibited by SGH." (PMID 33572615, 2021). "An elevated PSAT1, along with other enzymes within the SSP, has previously been reported in lung cancer." (PMID 34439090, 2021). "The increased expression of phosphoglycerate dehydrogenase (PHGDH) and the upregulation of both phosphoserine aminotransferase 1 (PSAT1) and phosphoserine phosphatase (PSPH) highlight the importance of the serine biosynthesis pathway in lung cancer biology." (PMID 31803611, 2019). "There is also a study showing the increased protein level of all three proteins (fold change: PHGDH: +3.62; PSAT 1: +6.94: PSPH: +1.27) in lung cancer tissue, when compared to corresponding non-tumorous tissue." (PMID 37376060, 2023). "In addition, PSAT1 promotes the nuclear translocation of pyruvate kinase M2 (PKM2) in response to EGFR activation, thus promoting lung cancer progression." (PMID 36699468, 2022). "Recent discoveries of the multifunctionality of metabolic enzymes in tumorigenic processes led us to explore a putative non-canonical function of PSAT1 involved in lung cancer progression." (PMID 34439090, 2021). "PSAT1 is a known target in NFE2L2/KEAP1 mutant lung cancer cell lines and was elevated in lung cancer and PDX tissues compared to adjacent lung tissues, suggesting serine biosynthesis could be an attractive target in SCC30,43." (PMID 31395880, 2019). "However, whether PSAT1 contributes to the molecular regulation of Wnt/β-catenin signaling by ATF4 in lung cancer cells is not clear." (PMID 33628101, 2021). "Additionally, we also want to know if PLK1 OE in other cancer cell type leads to the decrease of PHGDH, so we overexpressed PLK1 in lung cancer cell line A549 and found the decrease of PHGDH and no change of PSAT1." (PMID 40475404, 2025).